MMP2 (matrix metallopeptidase 2)
Diseases named in the same sentence as MMP2 in open-access papers (continued):
Sharing a sentence is not in itself a finding about the gene and the disease.
heart failure (continued). "In a systematic review and meta-analysis, only Timp1 levels were greater in hypertensive than normotensive patients, whereas both Timp1 and Mmp2 levels were greater in hypertensive patients with heart failure than hypertensive patients without heart failure." (PMID 28880918, 2017). "Among Tc+ individuals without cardiac insufficiency, only the MMP-2/MMP-9 ratio differed between those with and without ECG changes." (PMID 25275382, 2014). "Additionally, circulating MMP-2 and MMP-9 levels can reflect the effectiveness of treatment in heart failure patients and help identify those who may benefit from therapies targeting the MMP pathway." (PMID 39200884, 2024). "The hypomethylation of MMP2 and CTGF in dilated cardiomyopathy increased the expression of MMP2, a regulator of collagen turnover and fibrosis that is increased in patients with heart failure, and CTGF, which functions in extracellular matrix fibrosis and is highly expressed in failing hearts." (PMID 39596076, 2024). "Additionally, an increase in MMP-2 and MMP-9 produces extracellular matrix degradation, reduces the density of transverse tubules, and alters the management of Ca2+ in the myocardium of heart failure patients." (PMID 36831306, 2023). "MMP-2 and MMP-9 circulating levels can serve as indicators of efficiency of the therapy provided to heart failure (HF) patients, as well as for identification of patients who could benefit from particular therapeutic intervention via modification of MMP pathway." (PMID 32486345, 2020). "Furthermore, unlike chymase inhibitors, ACE inhibitors and ARBs currently in clinical use do not inhibit the activation of TGF-β and MMP-2, suggesting that chymase could serve as a novel therapeutic target for cardiac remodeling in conditions such as heart failure." (PMID 40943161, 2025). "We agree that some biomarkers, including MMP-2 and MMP-9, may reflect myocardial injury or heart failure regardless of T. cruzi infection." (PMID 31578449, 2019).
myocardial infarction (82 papers, 2010 to 2026). Gross necrosis of the myocardium, as a result of interruption of the blood supply to the area, as in coronary thrombosis. "This study shows that 5-HTT deficiency leads to age-dependent cardiac dysfunction and disrupted early healing after myocardial infarction, which was associated with increased local inflammation and MMP-2 expression during the early stage after MI." (PMID 34300270, 2021). "Much evidence suggest that MMP2 is associated with an increased risk of cardiovascular diseases, such as myocardial infarction and degenerative mitral valve disease." (PMID 33995494, 2021). "Although MMPs levels were not examined here, others have recently described in a model of lifelong exposure to BPA a decreased recovery after myocardial infarction associated with adverse cardiac remodeling due to increased MMP2 and MMP9 expression." (PMID 32144343, 2020). "The inhibition of MMP-2 is associated with less left ventricular adverse remodeling and higher survival after acute myocardial infarction in mice." (PMID 31205590, 2019). "Il1b gene polymorphisms influence the risk of myocardial infarction and ischemic stroke at a young age through NF-κB, iNOS, MMP-2 and Bax." (PMID 31827539, 2019). "In a Mexican population, a significant association between the specific MMP-2-1575 A/G polymorphism and occurrence of myocardial infarction has been established." (PMID 28446168, 2017). "High circulating levels of MMP-2 predict LV remodeling after myocardial infarction and are associated with hospital admission and mortality in patients with systolic HF." (PMID 27551966, 2016). "We demonstrated that 6 weeks of voluntary exercise was able to decrease the levels of serum and coronary effluent MMP-2 activity, reduce the myocardial infarct size, and improve the angina susceptibility of the heart." (PMID 25874025, 2015). "Underscoring the disease relevance of MMP-2-mediated cardiac injury, studies in humans have implicated MMP-2 in LV dysfunction and dysfunctional remodeling after myocardial infarction." (PMID 25309453, 2014). "Similarly, another study in AIM knockout mice showed a reduced incidence of ventricular aneurysm rupture after myocardial infarction, caused by a decrease in M1 macrophages and subsequent decreases in MMP-2 and -930." (PMID 38982113, 2024). "Moreover, higher MMP-2 levels were observed after acute myocardial infarction, and they were associated with larger left ventricular volumes." (PMID 38610612, 2024). "Clinical studies evaluating the effects of statins on MMP-2 inhibition (atorvastatin, rosuvastatin and pravastatin) in patients with HFrEF after acute myocardial infarction showed decreased serum MMP-2 levels associated with a reduction in the number of deaths and hospital readmission." (PMID 35893744, 2022). "MMP2 may be activated by oxidative/nitrosative stress, which is associated with myocardial infarction." (PMID 20565865, 2010). "Additionally, in patients with ST-elevation myocardial infarction undergoing percutaneous coronary intervention, higher plasma MMP-2-levels at baseline were associated with increased myocardial infarct size and decreased left ventricular function after four months of follow-up." (PMID 28446168, 2017). "After myocardial infarction (MI), there is a significant upsurge in the levels of matrix metalloproteinases (MMPs) in the heart, particularly MMP-2 and MMP-9, with MMP-2 expression exceeding that of MMP-9 by over 30 times." (PMID 39532649, 2025). "Previous studies have reported that haplotypes in the MMP-2 gene are associated with LVH, myocardial infarction, and impaired cardiac function." (PMID 40311090, 2025). "MMP2, a matrix metalloproteinase involved in tissue remodeling, is downregulated in response to acute myocardial infarction, reflecting impaired tissue repair mechanisms." (PMID 39513871, 2024).
myocardial infarction (continued). "In rat models, MMP-2 mRNA and protein levels increase within 24 hours following myocardial infarction, reaching their highest point around day 14 post-event." (PMID 39432214, 2024). "Post-myocardial infarction, MMP-2 levels surge due to stimulating cardiomyocytes and cardiac fibroblasts." (PMID 39432214, 2024). "In rat models, MMP-2 mRNA and protein levels elevate within 24-hour post-myocardial infarction, peaking around day 14 post-event." (PMID 39432214, 2024). "Targeted MMP2 knockdown improves survival after myocardial infarction by preventing macrophage infiltration and reducing the rate of left ventricular rupture." (PMID 37153746, 2023). "MMP‐2 is a multifunctional protein which expression is elevated in many cardiovascular pathologies (e.g., myocardial infarction, hypertensive heart disease) where tissue remodeling and inflammatory responses are perturbed." (PMID 37324843, 2023). "Acceleration of experimental diabetic nephropathy in MMP-2 knockout mice and prevention of cardiac ventricular fibrosis after myocardial infarction by MMP-2 secretion from mesenchymal cells also indicate the protective activity of MMP-2 in organ fibrosis." (PMID 37047672, 2023). "MMP-2 has also been considered a biomarker of LV remodeling in patients with HF who have suffered an acute myocardial infarction, with extensive areas of injury and decreased ejection fraction." (PMID 35893744, 2022). "Studies with knockout mice for MMP-2 were performed to confirm the participation of MMP-2 in HF after acute myocardial infarction." (PMID 35893744, 2022). "HA was further modified with β-cyclodextrin to sequester cholesterol-modified siRNA against matrix metalloproteinase 2 (MMP2), which was implicated in adverse remodeling after myocardial infarction." (PMID 36139035, 2022). "For example, TISAM, an N-sulfonylamino acid derivative, which selectively inhibits MMP-2, was used in a model of acute myocardial infarction, improving survival rate, preventing cardiac rupture and delaying post-infarction remodeling." (PMID 35893744, 2022). "At the same time, trimetazidine has reduced MMP-2 expression by decreasing oxidative stress in an animal model of myocardial infarction." (PMID 35893744, 2022). "MMP-2 can be considered a biomarker of HF, as higher plasma MMP-2 levels were found in patients with congestive HF, resulting from different etiologies (acute myocardial infarction, dilated cardiomyopathy and valvular disease)." (PMID 35893744, 2022). "In myocardial infarction (MI) murine model, miR-21 was upregulated and promoted the expression of MMP2 via a PTEN pathway in CFs, which probably influenced the turnover of ECM." (PMID 35966549, 2022). "MMP2 structure and function are correlated with increased remodeling after an acute myocardial infarction." (PMID 34449561, 2021). "Oxidative stress is involved in the expression of MMP-2, which is also relevant for myocardial infarction in mice." (PMID 29419744, 2018). "MMPI-1154 is a promising novel cardio-cytoprotective imidazole-carboxylic acid MMP-2 inhibitor lead candidate for the treatment of acute myocardial infarction." (PMID 29674965, 2018). "This indicates that the NAD(P)H-oxidase subunit p47phox is involved in the induction of MMP-2 expression in atherosclerosis and during myocardial infarction." (PMID 29419744, 2018). "MMP-2, which exhibits increased expression and activity following aortic stenosis, myocardial infarction (MI), and LV hypertrophy, is believed to have an adverse effect on cardiac remodeling." (PMID 29065927, 2017). "For example, these studies demonstrated that MMP-2 promotes ventricular rupture in the setting of experimental myocardial infarction." (PMID 23874529, 2013). "Treatment with E2 also leads to a reduction of fibrosis in animal models of MH and myocardial infarction (MI), and influences the collagen and matrix metalloproteinase 2 (MMP2) expression." (PMID 23227210, 2012).
myocardial infarction (continued). "MMP2 seems to have played at most, a minor role in the reduction of myocardial infarct size in this study, as its activity was reduced in both the RPO- and SFO-supplemented groups." (PMID 20565865, 2010). "In patients who had experienced an acute myocardial infarction, recombinant MMP‐2 induced the shedding of membrane‐bound CD100 from CD8+ T cells and the generation of soluble CD100, resulting in an elevation of CD8+ T‐cell cytotoxicity toward vascular endothelial cells." (PMID 40932621, 2025). "In case of myocardial infarction, antibodies against matrix metalloproteinase-2 (MMP2) or intercellular adhesion molecule-1 (ICAM-1) could enhance the ability of the microbubbles to increase the effects of imaging and delivery." (PMID 33066531, 2020). "MMP-2 impairs the cardioprotective response to oxidative stress via disturbed mitochondrial respiration and excessive lipid peroxidation as demonstrated in myocardial infarction in mice." (PMID 31205590, 2019). "Circulating levels of MMP-2/9 are also associated with the development of an acute myocardial infarction rather than stable angina, as the initial clinical presentation of coronary artery disease." (PMID 30513758, 2018). "In our study, we have successfully demonstrated the development of a novel, selective MMP-2 inhibitor for cardioprotection from an in silico compound library selection, through to the testing of the most promising compound against acute myocardial infarction, in an isolated rat heart model." (PMID 29674965, 2018). "Additionally, elevated MMP-2 levels were detected in the left ventricular myocardium of wild type mice during myocardial infarction as well as in atherosclerotic plaques, which suggests that MMP-2 expression is dependent on p47phox." (PMID 29419744, 2018). "Elevated circulating levels of MMP-2/9 are also strongly associated with the development of an acute myocardial infarction, rather than stable angina as the initial clinical presentation of CAD." (PMID 30513758, 2018). "Importantly, increased levels of MMP-2 have been observed in coronary blood samples from patients with myocardial infarction." (PMID 26526881, 2015). "Various animal models of myocardial infarction (MI) showed an elevation of MMP2, and MMP9, as well as activation of their endogenous inhibitors, TIMPs -1,-2, and -4." (PMID 32271823, 2020). "Pathologically, increased MMP-2 expression was observed after myocardial infarction (MI), which increases left ventricle rupture and delays post-MI remolding." (PMID 30718597, 2019). "Indeed, a study has demonstrated significant survival improvements after myocardial infarction (MI) in MMP-2 knockout mice, which could mainly be attributed to a reduced rate of early cardiac rupture and the subsequent development of LV remodeling and failure." (PMID 31487802, 2019). "Moreover, gelatinases A and B (MMP-2 and MMP-9) constitute risk factors for myocardial infarction whereas their tissue inhibitors TIMPs have an impact on postmyocardial infarction remodelling and correlate positively with left ventricular mass and wall thickness." (PMID 22383985, 2012). "A 2014 study reported the development of activatable cell-penetrating probes designed to assess MMP-2 and MMP-9 activity, though in the distinct context of post-myocardial infarction cardiac remodeling in murine models." (PMID 41206839, 2025). "After myocardial infarction, ACCF and ACCF-liposomes significantly reduced (P < 0.05) myocardial markers, including cTn-I, CK-MB, MMP-2, AST, LDH, and uric acid content." (PMID 40668529, 2025). "In animal models of myocardial infarction, heightened levels of tumor necrosis factor (TNF) within the myocardium directly correlate with increased production of local MMP-9 and MMP-2." (PMID 39432214, 2024). "For instance, Dan-Shen injection exerts anti-inflammatory effects by decreasing the expression of MMP2, MMP9, and myeloperoxidase (MPO) in a rat model of post-myocardial infarction." (PMID 38794213, 2024).
myocardial infarction (continued). "Carvedilol has also been reduced the levels of MMP-2 and MMP-9 an animal model of acute myocardial infarction." (PMID 37122872, 2023). "Finally, the levels of the MMP-2 were found elevated in the hearts of male rats during acute myocardial infarction (MI), with higher serum levels of the enzyme found to be associated with lower myocardial fibrosis only in females." (PMID 35893290, 2022). "In contrast to MMP-2 and MMP-9 where myocardial infarction (MI) induced increase of their levels/activities, MMP-28 levels decreased post-MI." (PMID 33923282, 2021). "Remodeling of the myocardial extracellular matrix requires proteolysis, and various studies have shown that MMP-2 and MMP-9 are prominently overexpressed after myocardial infarction." (PMID 32354131, 2020). "Curcumin treatment inhibits both MMP-2 and MMP-9 through its potent antioxidant action, promoting cardiac repair and ameliorating cardiac dysfunction following myocardial infarction." (PMID 31205590, 2019). "Aerobic exercise increased levels of serum netrin-1, myocardial netrin-1, and the DCC receptor and reduced the expression of myocardial MMP2 and MMP9 proteins, to improve the degree of fibrosis following myocardial infarction in rats." (PMID 30789913, 2019). "Curcumin pretreatment was proved to reduce MMP-2 and MMP-9 expression in extracellular matrix degradation after myocardial infarction, by inhibiting the expression of angiotensin II." (PMID 31205590, 2019). "Our study is the first to report the effect of curcumin nanoparticle pretreatment on MMP-2 and MMP-9 expression in myocardial infarction." (PMID 31205590, 2019). "The tracer binds to activated MMP-2/9, and has already been evaluated for PET imaging in a mouse melanoma xenograft model and a rat myocardial infarction model." (PMID 30513758, 2018). "At four weeks after MI, increases in MMP2 and MMP9 mRNA levels were observed in the Empty Bead group in both infarct and border regions of pig heart after myocardial infarction." (PMID 28003833, 2016). "A radiolabeled activatable cell penetrating peptide (ACPP) sensitive toward matrix metalloproteinases (MMP)-2 and -9 was successfully employed for MMP detection in the course of remodeling post-myocardial infarction in vivo." (PMID 26147581, 2015). "Meanwhile, recent studies showed that a variety of MMPs increase in the myocardium after myocardial infarction, including MMP-1, MMP-2, MMP-3, MMP-7, MMP-9, MMP-11, and so on." (PMID 25237357, 2014). "MMP2 and MMP9 are considered to play a pivotal role in myocardial remodeling in a number of cardiovascular diseases, including myocardial infarction (MI) and ischemic and idiopathic dilated cardiomyopathy (DCM)." (PMID 23710440, 2013). "Conversely, recombinant MMP‐2 has been shown to induce membrane‐bound CD100 shedding from CD8+ T cells and soluble CD100 generation, resulting in an enhancement of CD8+ T‐cell cytotoxicity toward endothelial cells in patients with acute myocardial infarction." (PMID 41243839, 2025). "Previously, we have shown that in in vitro and ex vivo study (isolated cardiomiocytes and Langendorf perfusion model), administration of doxycycline as MMP-2 and MMP-9 inhibitor protects the heart against consequences of ischemia and reperfusion after acute myocardial infarction." (PMID 38540247, 2024). "Colchicine reduced mRNA and protein expression of MMP2 in vitro, mitigated mRNA expression of MMP-3, MMP-9, and MMP-10 in aortas of mice and abolished the relative mRNA expression of MMP-9 in infarct area of myocardium after myocardial infarction in mice." (PMID 38001470, 2023). "Additionally, plaque destabilization was boosted through the increase in expression of matrix metalloproteinase (MMP)-2 and MMP-9 which was evident in blood samples derived from male patients with acute myocardial infarction." (PMID 37943388, 2023).